MMP8 (matrix metallopeptidase 8)
Diseases named in the same sentence as MMP8 in open-access papers (continued):
Sharing a sentence is not in itself a finding about the gene and the disease.
periodontitis (continued). "The aim of this study was to determine the diagnostic utility of an MMP‐8 biosensor assay in differentiating periodontal health from gingivitis and periodontitis and compare it with an established time‐resolved immunofluorescence assay (IFMA) and enzyme‐linked immunosorbent assay (ELISA)." (PMID 35304757, 2022). "Thus, the aim of the present study was to evaluate salivary concentrations of IL-1β, IL-6, MMP-8, and IL-10 in healthy and periodontitis patients and to assess the association between these biomarkers levels and clinical parameters in a Moroccan population." (PMID 35368315, 2022). "Meanwhile, the results of Pearson correlation test showed negative correlation between the miR-1226 expression levels and the probing pocket depth (r = -0.806, P < 0.001), attachment loss (r = -0.764, P < 0.001), and MMP-8 concentration (r = -0.654, P < 0.001) in patients with periodontitis." (PMID 34592963, 2021). "As MMP-8 has been suggested for use as diagnostic aid for periodontitis, it may also be useful in the diagnosis of systemic conditions, such as diabetes." (PMID 33916950, 2021). "Furthermore, MMP‐8 has been shown to be associated with periodontitis among both sexes and even in pediatric population, and thus, these differences between the groups are as expected, and insignificant in this context." (PMID 34448550, 2021). "The salivary level of active MMP‐8 was statistically significantly associated with periodontitis." (PMID 34448550, 2021). "It has been shown that MPO/MMP-8 could represent the discriminatory biomarkers for the site specific diagnosis of periodontitis, and their association might reflect the disease severity." (PMID 30669541, 2019). "HIV has been associated with periodontitis, and in theory, it could also have a modifying effect on MMP-8 levels." (PMID 30223547, 2018). "In addition, salivary levels of IL-1β and MMP-8 are significantly associated with severe periodontitis compared to healthy controls." (PMID 28117682, 2017). "Moreover, the combination of the levels of three selected salivary biomarkers, namely MMP-8, IL-1β, and P. gingivalis, was associated with periodontitis better than any of the markers alone." (PMID 26484315, 2015). "Furthermore, salivary MMP-8 levels are associated with progressive loss of attachment in periodontitis." (PMID 26132583, 2015). "High values of MMP-8 in children of group 2 with terminal CKD on hemodialysis could be associated with a mild degree of periodontitis detected by changes in periodontal indices, as well as with the beginning of osteodystrophic changes in hard tissues of the oral cavity." (PMID 40363983, 2025). "Notably, MMP-8 is abundant in inflammatory conditions, with elevated levels strongly associated with periodontal tissue degradation, which highlights its potential value as a biochemical indicator of the severity and activity of periodontitis." (PMID 39795606, 2024). "However, a significant correlation with periodontitis risk was only found in MMP-8 −799 C/T polymorphism, and it has been reported that T allele carriers have more MMP-8 production in the periodontal environment with bacterial challenge compared to non-T allele carriers." (PMID 27194818, 2016). "MMP-8 assays are carried out on saliva or gingival fluid, and it has been demonstrated that patients with periodontitis have greater MMP-8 levels than healthy subjects do37." (PMID 40676110, 2025). "In patients with periodontitis, the latent proMMP-8 enzyme thus becomes catalytically active MMP-8 (aMMP-8) and proteolytically and collagenolytically tissue-destructive due to its abundant presence and destructive action." (PMID 40136755, 2025). "As the second outcome of interest, we analyzed activated MMP8 (aMMP-8) levels in periodontitis patients (n = 573) and healthy participants (n = 364)." (PMID 40045958, 2025).
periodontitis (continued). "After the removal of outlier studies (n = 29), a random effect meta-analysis yielded a significantly high MMP8 and aMMP8 levels in periodontitis patients (SMD: 1.97, 95% CI: 1.48–2.46, p < 0.0001, I2 = 90.2%)." (PMID 40045958, 2025). "Our analysis identified significant differences in MMP-8 and aMMP-8 levels between periodontitis cases and healthy controls, supporting their potential as diagnostic biomarkers." (PMID 40045958, 2025). "Interleukin-1β (IL-1β) and matrix metalloproteinases-8 (MMP-8) are considered typical salivary biomarkers for early diagnosis and progression monitoring of periodontitis." (PMID 40508178, 2025). "Studies included in the meta-analysis analyzing MMP8 and aMMP8 levels in patients with periodontitis and healthy controls." (PMID 40045958, 2025). "The expression and activation of MMP-8 therefore reflect the severity of inflammatory changes as well as the degree of tissue degradation in periodontitis." (PMID 40558889, 2025). "While extensive research has established MMP-8 as a key mediator of connective tissue destruction and inflammation regulation in periodontitis, fewer studies have examined its role in peri-implantitis." (PMID 40423054, 2025). "MMP-8 plays a central role in extracellular matrix remodeling and turnover, contributing to tissue destruction and inflammation with periodontitis events." (PMID 40045958, 2025). "MMP-8 shows promise as the top biomarker for predicting, diagnosing, and gauging the progression of periodontitis." (PMID 40045958, 2025). "Our research is also the first to assess the level of MMP-8 as an indicator of the effectiveness of periodontitis treatment after the use of i-PRF." (PMID 40558889, 2025). "Elevated levels of MMP‐8 and MMP‐9 are associated with more severe periodontitis and an increased risk of diabetes mellitus." (PMID 39811802, 2025). "To investigate periodontitis, we used results from Greece from the study Active MMP-8 (aMMP-8) as a Grading and Staging Biomarker in the Periodontitis Classification." (PMID 39941225, 2025). "Periodontal bacteria stimulate immune cells, triggering the production and release of MMP-8 into the bloodstream, leading to elevated serum MMP-8 levels in patients with generalized and aggressive periodontitis." (PMID 40283677, 2025). "Studies have shown that MMP-8 is a potential biomarker of periodontal degradation in patients with periodontitis alone and with metabolic diseases like diabetes mellitus or other risk factors like smoking." (PMID 41300956, 2025). "Notably, it is also important to consider that, depending on the need for MMP-8 testing, oral rinse may be a suitable alternative to saliva as an oral fluid analytic matrix for case‐finding and diagnostic differentiation of periodontitis, particularly in patients with systemic diseases." (PMID 41075005, 2025). "As previously reported, activity levels of the salivary biomarkers MMP-8, MMP-9, and IL-1β have been linked to periodontitis." (PMID 41002732, 2025). "Increased MMP-8 levels are associated with bacteria such as Fusobacterium nucleatum, Tannerella forsythia, and Treponema denticola, which is why MMP-8 is considered an accurate biomarker for the diagnosis of periodontitis." (PMID 41002732, 2025). "Pooled results indicated significantly higher levels of MMP-8 and aMMP-8 in periodontitis cases compared to healthy controls (SMD: 2.71, 95% CI: 1.04–4.38, p = 0.002) with substantial heterogeneity (I2 = 94.5%)." (PMID 40045958, 2025). "In patients with periodontitis, the expression and activation of MMPs, especially MMP-8 and MMP-9, significantly influence tissue degradation." (PMID 41002732, 2025). "A total of 25 and 10 studies, respectively, examining MMP-8 and aMMP-8 levels in periodontitis patients compared to healthy controls were included in the current meta-analysis." (PMID 40045958, 2025). "The study found that RT increased the levels of MMP-8 and MMP-9 and were linked to the clinical worsening of periodontitis." (PMID 40545647, 2025).
periodontitis (continued). "Patients with chronic periodontitis demonstrate elevated levels of matrix metalloproteinase-8 (MMP-8) in gingival crevicular fluid, saliva, and serum compared to individuals with gingivitis or periodontally healthy controls." (PMID 41586318, 2025). "Several studies have established a link between matrix metalloproteinases (MMPs) and periodontitis, with MMP-8 being the predominant collagenase (80%) detected and analyzed in gingival tissue and gingival crevicular fluid (GCF)." (PMID 40283677, 2025). "To assess the effects of ZP on the tissue-destructive enzyme activity in periodontitis, we examined the expression of MMP-8." (PMID 41154468, 2025). "A systematic literature search was conducted utilizing PubMed, Embase, Web of Science, and Cochrane Library databases up to October 2023, yielding 35 studies that quantified MMP-8 or aMMP-8 in saliva from patients with periodontitis and healthy controls." (PMID 40045958, 2025). "In one study, patients with severe periodontitis were found to have higher salivary concentrations of IL-1β and MMP-8." (PMID 40528176, 2025). "The findings support the potential of MMP-8 and aMMP-8 as biomarkers for periodontitis, although substantial heterogeneity and methodological differences among studies pose challenges." (PMID 40045958, 2025). "For instance, MMP-8 levels exhibited a wider range and more pronounced outliers in patients with Grade C periodontitis, suggesting greater heterogeneity in inflammatory response among those with rapid disease progression." (PMID 40283677, 2025). "Collagenase activity in GCF and MMP-8 concentrations were found to correlate with the amount of type I collagen breakdown products in sites with active periodontitis compared with inactive sites." (PMID 41440646, 2025). "Among the various salivary biomarkers, matrix metalloproteinase-8 (MMP-8) has demonstrated particular promise in periodontitis disease differentiation." (PMID 41149323, 2025). "Results: aMMP-8 is the superior biomarker for grade of periodontitis (progression rate) when compared to the total latent/proform MMP-8 (total-MMP-8) and microbial lipopolysaccharide (LPS/LAL) activity." (PMID 40136755, 2025). "Our meta-analysis makes a significant contribution to the literature by synthesizing the available evidence on salivary MMP-8/aMMP-8 levels during periodontitis events." (PMID 40045958, 2025). "Studies showed an overall effect favoring high MMP8 levels in periodontitis cases (unstimulated saliva collection: SMD: 1.61, 95% CI: 1.04–2.17, I2 = 92% and stimulated saliva collection: SMD: 0.69, 95% CI: 0.32–1.06, I2 = 57%)." (PMID 40045958, 2025). "MMP-2, MMP-8, MMP-9, and MMP-20 have been implicated in caries-induced dentine matrix destruction, as well as in periodontitis." (PMID 40332093, 2025). "Our analysis corroborated the observation that both MMP-8 and aMMP-8 levels are elevated in the presence of periodontitis, albeit encountering notably high heterogeneity for both biomarker types." (PMID 40045958, 2025). "Elevated levels of pro-inflammatory cytokines, such as IL-1β and IL-6, along with matrix metalloproteinases like MMP-8, contribute to the degradation of connective tissue and bone resorption, driving the clinical manifestations of periodontitis." (PMID 40283677, 2025). "The impact of diabetes on periodontal disease is demonstrated by the significant correlation between periodontitis and salivary MMP-8 activity." (PMID 40299548, 2025). "Salivary biomarkers such as salivary matrix metalloproteinase-8 (MMP-8) and its activated form (aMMP-8) have been studied for their roles in tissue degradation and inflammation in periodontitis." (PMID 40045958, 2025). "The findings from this study provide valuable insights into the potential role of MMP-8 as a biomarker and the broader implications of salivary analysis in periodontitis diagnosis." (PMID 40045958, 2025).
periodontitis (continued). "MMP-8 also serves as a biomarker for various diseases, and salivary MMP-8 is used as a biomarker in detecting periodontitis." (PMID 41002342, 2025). "Our data indicate that the development of diabetes can increase the expression of MMP-8 (total MMP-8) in severe periodontitis cases." (PMID 39353614, 2025). "Overexpression and overactivation of MMPs result in periodontal tissue destruction, and profound MMP-8 and MMP-9 elevations are associated with periodontitis severity." (PMID 40332093, 2025). "Highest levels were observed in periodontitis group just as with the MMP-8 followed by gingivitis group." (PMID 38086426, 2024). "The salivary MMP-8 level exhibits a significant elevation in individuals diagnosed with periodontitis in contrast to both healthy controls and those affected with gingivitis." (PMID 39641024, 2024). "For diabetic patients with periodontitis, the level of salivary MMP‐8 is considerably higher than for other groups." (PMID 38433295, 2024). "Patients with periodontitis presented significantly higher salivary MMP-8 levels (MD = 273.26, CI: 194.42; 352.10)." (PMID 39641024, 2024). "A more comprehensive evaluation of additional combinations of periodontitis biomarkers, beyond MMP-8 with IL-1β and IL-6, is warranted, along with the development of more sensitive biomarker assays." (PMID 39554809, 2024). "The theory of the indirect effects of periodontitis on premature or low birth-weight births involves elevated levels of matrix metalloproteinase-8 (MMP-8) and matrix metalloproteinase-9 (MMP-9)." (PMID 38672972, 2024). "In saliva, MMP-8 combined with IL-1β, and IL-6, are excellent for detecting periodontitis and identifying non-periodontitis." (PMID 39554809, 2024). "Some studies also indicate correlations between MMP-8 levels and the presence of microorganisms involved in the pathogenesis of periodontitis." (PMID 38473967, 2024). "Active matrix metalloproteinase-8 (aMMP-8) is an important factor in periodontitis and collagenolytic tissue destruction in the periodontium, which total/latent MMP-8 (nowadays abbreviated by MMP-8) lacks." (PMID 39767238, 2024). "We evaluated all studies that compared different laboratory techniques for measuring salivary MMP-8 levels in periodontitis and gingivitis patients, alongside healthy controls." (PMID 39641024, 2024). "MMP-8 (–799C/T) and MMP13 (–77A/G) can be associated with chronic forms of periodontitis in the Indian population." (PMID 39553301, 2024). "Studies have shown that oral rinse samples from periodontitis patients contain substantially higher levels of MMP-8 and TPA than those from controls." (PMID 39554809, 2024). "Matrix metalloproteinase-8 (MMP-8) is the major collagenase in periodontitis and its active form aMMP-8 is the most significant cause of periodontal tissue destruction." (PMID 39272635, 2024). "In the group of patients with periodontitis, salivary MMP-8 levels were significantly higher (MD = 112.04, CI: 56.15; 167.92)." (PMID 39641024, 2024). "MMP-8 combined with IL-1β can distinguish between periodontal health and periodontitis, even in patients with systemic inflammatory diseases such as type 2 diabetes mellitus." (PMID 39554809, 2024). "MMP-8 is a potent biomarker candidate for identifying alveolar bone degradation and is by far, the most thoroughly studiedbiomarker for periodontitis and peri-implantitis." (PMID 39917206, 2024). "Posthoc analysis by Tukey's test revealed that MMP-8 levels were higher in gingivitis and periodontitis groups as compared with healthy controls." (PMID 38086426, 2024). "MMP-8 levels were found to be greater in gingivitis and periodontitis groups compared with healthy controls." (PMID 38086426, 2024). "The purpose of this study was to compare the quantity of MMP‐8 in the saliva of patients with type 2 diabetes and periodontitis to the amount in the saliva of individuals with periodontitis but normal blood sugar levels." (PMID 38433295, 2024).
periodontitis (continued). "Combining salivary biomarkers such as MMP-8 and IL-1B can prove to be a valuable key to diagnose gingivitis and periodontitis." (PMID 38086426, 2024). "Increased concentrations of MMP-2, MMP-7, and circulating MMP-8 have been found in patients with IPF while connective tissue deterioration in chronic periodontitis has been shown to be significantly influenced by these MMPs." (PMID 38420070, 2024). "This study highlights the importance of monitoring salivary MMP‐8 levels in patients with periodontitis, especially those with diabetes." (PMID 38433295, 2024). "They found that in eight studies, the levels of MMP-8 in the saliva of periodontitis patients were significantly higher compared to healthy individuals." (PMID 38168591, 2024). "Similar to previous studies, MMP-8 concentrations in saliva correlate with indicators of periodontitis." (PMID 38473967, 2024). "It has been shown that matrix metalloproteinase-8 (MMP-8), as a collagenase in gingival connective tissue, is an early biomarker of periodontitis that can be measured not only with laboratory methods but also with chair-side tests." (PMID 39336968, 2024). "This study is the first to systematically investigate if salivary MMP-8 can distinguish periodontitis and gingivitis from periodontal health, respectively, and also, distinguish between the two diseases, gingivitis and periodontitis." (PMID 39641024, 2024). "Overall, MMP-8 level measurement has a high potential to set a new foundation and standard for periodontitis prevention." (PMID 39641024, 2024). "Due to the high heterogeneity and publication bias, further studies are needed to identify the correlation between MMP-8 and periodontitis." (PMID 38168591, 2024). "Increased levels of salivary IL-1β, IL-6, and MMP-8 were observed in individuals with periodontitis." (PMID 39410587, 2024). "In this regard, many studies using total MMP-8 as the oral fluid periodontitis and periimplantitis biomarker have failed." (PMID 38786309, 2024). "Meta-analysis performed for salivary biomarkers showed the highest sensitivity for the diagnosis of periodontitis for IL-1β (77.8%) and MMP-8 (72.5%), and the highest specificity for MMP-9 (81.5%) and IL-1β (78%)." (PMID 39684335, 2024). "In contrast, the total MMP-8 assay and the other biomarkers were less efficient and precise in distinguishing patients with periodontitis from healthy controls." (PMID 39273368, 2024). "MMP-8 combined with chitinase accurately classified participants with 87.2% accuracy, distinguishing periodontitis from periodontal health/gingivitis." (PMID 39554809, 2024). "IL-1 and MMP-8 are two main immunological factors involved in the tissue destruction of periodontitis." (PMID 38817441, 2024). "On the other hand, male samples showed high levels in periodontitis as compared with the control group that was constant in all comparisons in MMP-8 analysis (Figs. 3and4)." (PMID 38086426, 2024). "Saliva or peri-implant crevicular fluid samples showed elevated MMP-8 levels,particularly in patients with concurrent periodontitis." (PMID 39917206, 2024). "MMP-8’s good sensitivity and excellent specificity make it the most effective biomarker for diagnosing periodontitis in systemically healthy participants, with a median sensitivity and specificity of 76.7% and 92.0%, respectively." (PMID 39554809, 2024). "MMP-8 concentrations positively correlate with clinical parameters of periodontitis severity such as CAL (clinical attachment level) and plaque index (PI)." (PMID 38473967, 2024). "The aim of the present study was to gather current knowledge on the importance of MMP-8 in periodontitis and also the usefulness of this enzyme in the diagnosis of this condition." (PMID 38473967, 2024). "Patients with periodontitis and diabetes had the highest levels of salivary MMP‐8, while the control group had the lowest levels." (PMID 38433295, 2024).